SNORD20 (small nucleolar RNA, C/D box 20)
Synonyms: U20; RNU20
Gene: Small nucleolar RNA gene on chromosome 2 (231,456,444 to 231,456,523, reverse strand). Ensembl gene ENSG00000207280.
Gene Ontology:
Biological process: RNA processing
Cellular component: nucleolus
Homologues: Orthologues: chimpanzee SNORD20 (100% identical), mouse Gm55462 (100% identical), macaque SNORD20 (99% identical), rat Snord20 (99% identical), guinea pig SNORD20 (98% identical), pig SNORD20 (98% identical), rabbit SNORD20 (85% identical).